ZNF595 (zinc finger protein 595)
Description:
May be involved in transcriptional regulation.
Synonyms: FLJ31740
Tractability: PROTAC: ubiquitination databases record sites on it.
Gene: Protein-coding gene on chromosome 4 (53,286 to 88,208, forward strand). Ensembl gene ENSG00000272602.
Subcellular location: Nucleus
Pathways (Reactome):
Gene expression (Transcription): Generic Transcription Pathway
Gene Ontology:
Molecular function: protein binding; DNA-binding transcription factor activity, RNA polymerase II-specific; RNA polymerase II cis-regulatory region sequence-specific DNA binding
Biological process: regulation of transcription by RNA polymerase II; negative regulation of transcription by RNA polymerase II; regulation of DNA-templated transcription
Cellular component: nucleus
Genetic constraint (gnomAD): Loss-of-function variants: 27 observed, 35.36 expected, observed/expected ratio (o/e) 0.76, 90% interval 0.56 to 1.05. The upper end of that interval is the gene's LOEUF score, 1.05, which puts it in group 4 of 6, group 1 being the genes least tolerant of losing a copy. Missense variants: 729 observed, 720.99 expected, observed/expected ratio (o/e) 1.01, 90% interval 0.95 to 1.08. Synonymous variants: 255 observed, 238.61 expected, observed/expected ratio (o/e) 1.07, 90% interval 0.96 to 1.19.
Homologues: Orthologues: chimpanzee ZNF595 (99% identical), macaque ZNF595 (96% identical). Paralogues in human: ZNF493 (65% identical), ZNF732 (63% identical), ZNF724 (56% identical), ZNF728 (56% identical), ZNF726 (56% identical), ZNF254 (55% identical), ZNF708 (55% identical), ZNF429 (54% identical), ZNF85 (53% identical), ZNF93 (53% identical), ZNF141 (53% identical), ZNF718 (52% identical), and 164 more.
Diseases named in the same sentence as ZNF595 in open-access papers:
ZNF595 is named in the same sentence as 12 diseases in open-access papers, as found by Europe PMC text mining. Sharing a sentence is not in itself a finding about the gene and the disease. The quoted sentences say what the papers report.
dengue fever (3 papers, 2022 to 2025). "ZNF595 has acceptable AUC in discriminating dengue hemorrhagic fever (DHF) from dengue fever (DF) in whole acute stages." (PMID 35918744, 2022). "While ZNF595 has already been found crucial in human gastric cancer and Dengue, its role in IDD remains unclear." (PMID 41023110, 2025). "Our research was the first to show that CD38 and ZNF595 had clinical significance in the stage and severity of Dengue and that they could be used as biomarkers to distinguish clinical stages and severity for Dengue patients." (PMID 35918744, 2022). "In another study of stage-related and severity-related biomarkers, they have found CD38 and ZNF595 as significant biomarkers; CD38 can distinguish different clinical stages of dengue, while ZNF595 can differentiate between dengue fever (DF) and DHF." (PMID 40100920, 2025).
breast carcinoma (2 papers, 2025). "These aberrations highlighted well-known breast cancer-associated genes, such as MDM4, ZNF595, FGFR4, HIST1H1B, TPD52, DECR1, GRB7, and JUP55." (PMID 40162205, 2025).
gastric cancer (2 papers, 2024 to 2025). A primary or metastatic malignant neoplasm involving the stomach. "For mncfDNA candidates, mutations in ZNF595 have been indicated as a potential germline mutation in familial lung cancer and a region for prevalent somatic mutations in gastric cancer." (PMID 38797520, 2024).
schizophrenia (1 paper, 2023). A major psychotic disorder characterized by abnormalities in the perception or expression of reality. "In schizophrenia (SCZ) patients, nonsense de novo mutations of ZNF595 are common." (PMID 36952494, 2023).
Stroke (1 paper, 2023). Sudden impairment of blood flow to a part of the brain due to occlusion or rupture of an artery to the brain. "Co-expressed hub genes of EIF4E3, ZNF595, ZNF700, MATR3, ACKR4, ANXA3, SEPSECS-AS1, and RNF166 were significantly associated with AF-related stroke." (PMID 36952494, 2023). "Based on the results of DEG3 and ROC curves in GSE66724 and GSE58294, we filtered eight hub genes of AF-related stroke (AUC > 0.8), including EIF4E3, ZNF595, ZNF700, MATR3, ACKR4, ANXA3, SEPSECS-AS1, and RNF166." (PMID 36952494, 2023). "Hub genes EIF4E3, ZNF595, ZNF700, MATR3, ACKR4, ANXA3, SEPSECS-AS1, and RNF166 have potential as novel biomarkers and therapeutic targets in AF-related stroke." (PMID 36952494, 2023). "The hub genes of EIF4E3, ZNF595, ZNF700, MATR3, ACKR4, ANXA3, SEPSECS-AS1, and RNF166 may link AF and secondary stroke." (PMID 36952494, 2023).
tumor (4 papers, 2017 to 2024). "The transcriptional programs regulated by TBX21, ZNF595, FOSL2, ZNF83, ZNF484, IKZF2, and ELK3 were found to be significantly activated in tumor-reactive T cells." (PMID 39243082, 2024).
ZNF595 also shares sentences with these, for which no sentence is quoted: cancer (2 papers); cardiac hypertrophy (1); Dengue hemorrhagic fever (1); lung carcinoma (1); meningioma (1); prostate (1).